ANP32E (acidic nuclear phosphoprotein 32 family member E)
Description:
Histone chaperone that specifically mediates the genome-wide removal of histone H2A.Z/H2AZ1 from the nucleosome: removes H2A.Z/H2AZ1 from its normal sites of deposition, especially from enhancer and insulator regions. Not involved in deposition of H2A.Z/H2AZ1 in the nucleosome. May stabilize the evicted H2A.Z/H2AZ1-H2B dimer, thus shifting the equilibrium towards dissociation and the off-chromatin state. Inhibits activity of protein phosphatase 2A (PP2A). Does not inhibit protein phosphatase 1. May play a role in cerebellar development and synaptogenesis.
Synonyms: LANP-L; LANPL; MGC5350
Tractability: PROTAC: UniProt records ubiquitination sites on it; ubiquitination databases record sites on it; its protein half-life has been measured.
Gene: Protein-coding gene on chromosome 1 (150,218,417 to 150,236,202, reverse strand). Ensembl gene ENSG00000143401.
Subcellular location: Cytoplasm; Nucleus
Subcellular location (Human Protein Atlas): Nucleoplasm; Centrosome; Cytosol
Gene Ontology:
Molecular function: histone binding; histone chaperone activity; protein binding; protein folding chaperone; phosphatase inhibitor activity
Biological process: regulation of apoptotic process; protein folding
Cellular component: nucleus; Swr1 complex; cytoplasmic vesicle; cytoplasm; glutamatergic synapse; postsynaptic density membrane; postsynaptic endosome membrane; synaptic vesicle membrane
Genetic constraint (gnomAD): Loss-of-function variants: 12 observed, 25.51 expected, observed/expected ratio (o/e) 0.47, 90% interval 0.3 to 0.76. The synonymous counts are far from expectation, so gnomAD's model fits this gene poorly and the ratio says little. Missense variants: 141 observed, 234.89 expected, observed/expected ratio (o/e) 0.6, 90% interval 0.52 to 0.69. Synonymous variants: 63 observed, 91.66 expected, observed/expected ratio (o/e) 0.69, 90% interval 0.56 to 0.85.
Homologues: Orthologues: chimpanzee ANP32E (100% identical), macaque ANP32E (98% identical), mouse Anp32e (91% identical), dog ANP32E (90% identical), guinea pig ANP32E (89% identical), pig ANP32E (83% identical), rat Anp32e (78% identical), zebrafish anp32e (72% identical), tropical clawed frog anp32e (70% identical), Drosophila melanogaster Mapmodulin (46% identical), Caenorhabditis elegans F33H2.3 (35% identical), Caenorhabditis elegans T19H12.2 (34% identical). Paralogues in human: ANP32A (61% identical), ANP32B (57% identical), ANP32D (32% identical).
Diseases named in the same sentence as ANP32E in open-access papers:
ANP32E is named in the same sentence as 26 diseases in open-access papers, as found by Europe PMC text mining. Sharing a sentence is not in itself a finding about the gene and the disease. The quoted sentences say what the papers report.
breast carcinoma (13 papers, 2017 to 2025). "ANP32E has been recognized as part of a six-gene profile linked to lung metastases in the setting of breast cancer." (PMID 39968094, 2025). "For example, the downregulation of miRNA-141 in breast cancer cells was associated with cell migration and invasion: involvement of ANP32E targeting." (PMID 37993951, 2023). "Here, we discovered that ANP32E is highly expressed in TNBC cells compared to other types of breast cancer, and high levels of ANP32E expression are associated with shorter survival times and higher risks of disease relapse in TNBC." (PMID 29633513, 2018). "Additionally, ANP32E has been implicated in breast cancer, where it inhibits cell proliferation and encourages apoptosis; thus, its downregulation may lead to more aggressive tumor behavior." (PMID 40438679, 2025). "Interestingly, a recent study suggests that ANP32E may be an independent prognostic marker for human breast cancers, where higher ANP32E protein levels are associated with the TNBC subtype and correlated with a shorter overall and disease-free survival." (PMID 34922480, 2021). "SMYD3 suppresses the methylation of H2A.Z1, thereby inhibiting Anp32e-mediated dissociation of H2A.Z1 from chromatin, increasing cyclin A1 expression, and encouraging breast cancer progression." (PMID 39199381, 2024). "ANP32E knockdown has been shown to inhibit the proliferation, migration and metastasis of breast cancer cells." (PMID 35387118, 2022). "We therefore propose a model in which ANP32E has two separate functions in breast cancer, depending on tumor subtype or the differentiation state of the cell of origin." (PMID 34922480, 2021). "The inhibition of miR-141 regulates cell invasion and migration in breast cancer cells by targeting ANP32E." (PMID 33686957, 2021). "Although the significance of ANP32E in breast cancer is poorly studied, several articles have reported an important role for ANP32E in myeloma and gastric cancer." (PMID 29633513, 2018). "In breast cancer, a six‐gene signature consisting of DSC2, TFCP2L1, UGT8, ITGB8, ANP32E, and FERMT1 is associated with lung metastasis." (PMID 29633513, 2018). "The methyltransferase SET and MYND domain-containing protein 3 (SMYD3) enables H2A.Z1 methylation, thereby reducing the removal of H2A.Z1 from chromatin by Anp32e, increasing cell cycle-related protein expression, and promoting breast cancer cell proliferation." (PMID 39199381, 2024). "Additionally, knockdown of ANP32E by siRNA lentivirus inhibits the cancerous cell proliferative, migratory, and invasive capabilities in breast cancer." (PMID 34551785, 2021). "Our results indicate that ANP32E may function through chromatin state regulation to control breast cancer differentiation and tumor plasticity." (PMID 34922480, 2021). "Dys-regulation of ANP32E contributes to the migration and invasion of breast cancer cells." (PMID 33148205, 2020). "Interestingly, ANP32E is a part of Landmaine’s “six gene signature” that is used for the screening of distant relapse of breast cancer metastasis." (PMID 32257110, 2020). "Acidic nuclear phosphoprotein 32 family member E (ANP32E), a specific H2A.Z chaperone, has been shown to contribute to breast cancer development." (PMID 33148205, 2020). "Here, we report that acidic nuclear phosphoprotein 32 family member E (ANP32E), which promotes cell proliferation in mammalian development, is highly expressed in TNBC cells compared to other types of breast cancer." (PMID 29633513, 2018). "To study the relationship between ANP32E and TNBC, we assessed the expression of ANP32E among different types of breast cancer using the The Cancer Genome Atlas (TCGA) database." (PMID 29633513, 2018). "ANP32E along with desmocollin 2 (DSC2), UDP glycosyltransferase 8 (UGT8), Integrin subunit beta 8 (ITGB8) and Fermitin family member 1 (FERMT1) is found to predict lung metastasis of breast cancer patients and has been used as prognostic marker." (PMID 32257110, 2020).
breast carcinoma (continued). "Furthermore, we randomly chose eight breast cancer tissues (four TNBC tissues and four non‐TNBC tissues) to assess protein and mRNA expression levels of ANP32E." (PMID 29633513, 2018). "However, the precise mechanisms by which ANP32E functions to support breast cancer growth and its role in defining breast cancer phenotypes has not been fully established." (PMID 34922480, 2021). "Otherwise, Anp32e promoted breast cancer cell proliferation and anti‐apoptosis ability by inhibiting phosphatase 2A, a tumor suppressor that represses the PI3K/AKT pathway, in a mouse model which indicated that ANP32E might promote cell cycle progression through multiple pathways." (PMID 29633513, 2018). "Finally, we found that expression for the chromatin factor ANP32E was anti-correlated with tumor progression and with accessibility at FOXA1 binding sites among group 2 and 3 tumors, suggestive of a novel mechanism by which FOXA1 activity may be regulated in breast cancer tumors." (PMID 34922480, 2021).
pancreatic cancer (5 papers, 2020 to 2025). "Upregulation of ANP32e expression is associated with increased proliferation of several cancers including triple-negative breast cancer, childhood acute myeloid leukemia, mesothelioma, thyroid carcinoma, medulloblastoma, pancreatic cancer, and lung cancer." (PMID 38482865, 2024). "Upregulation of ANP32e expression is associated with increased proliferation of cancers including triple-negative breast cancer, childhood acute myeloid leukemia, mesothelioma, thyroid carcinoma, medulloblastoma, pancreatic cancer, and lung cancer." (PMID 38482865, 2024). "The overexpression of miR-202-5p suppresses the proliferation of pancreatic cancer stem cells (PCSCs) by targeting ANP32E and promotes their apoptosis." (PMID 40710326, 2025). "ANP32E is overexpressed in pancreatic cancer compared with normal tissues, and its silencing inhibits cell proliferation and colony formation in vitro." (PMID 39852534, 2025). "Up-regulation of ANP32E promoted the proliferation, colony growth and migration of pancreatic cancer cells." (PMID 33148205, 2020). "ANP32E promotes the proliferation and migration of pancreatic cancer cells through up-regulation and activation of β-catenin/cyclin D1 signaling." (PMID 33148205, 2020). "Our results propose that ANP32E functions as an oncogene in pancreatic cancer via activating β-catenin." (PMID 33148205, 2020). "To study the clinical relevance of ANP32E in pancreatic cancer, we downloaded the transcript abundance of ANP32E and pancreatic adenocarcinoma (PAAD) patients’ survival information from TCGA database." (PMID 33148205, 2020). "ANP32E was up-regulated in pancreatic cancer tissues and cells." (PMID 33148205, 2020). "Our results propose that ANP32E functions as an oncogene in pancreatic cancer." (PMID 33148205, 2020). "To determine whether ANP32E functions as an oncogene in pancreatic cancer, we used lentivirus to knock down ANP32E in pancreatic cancer cells PANC1 and MIA." (PMID 33148205, 2020). "Collectively, ANP32E enhanced the migration of pancreatic cancer cells." (PMID 33148205, 2020). "Taken together, ANP32E promotes pancreatic cancer through activating β-catenin." (PMID 33148205, 2020). "Next, we assessed the role of ANP32E on pancreatic cancer cell migration." (PMID 33148205, 2020). "Collectively, ANP32E functions as an oncogene in pancreatic cancer." (PMID 33148205, 2020). "However, the involvement of ANP32E in pancreatic cancer is unclear." (PMID 33148205, 2020). "miR-202-5p functions as a tumor suppressor and demonstrates reduced expression in pancreatic cancer tissues and cells, but the expression levels of NORAD and ANP32E are elevated." (PMID 40710326, 2025).
triple-negative breast carcinoma (5 papers, 2020 to 2024). An invasive breast carcinoma which is negative for expression of estrogen receptor (ER), progesterone receptor (PR), and human epidermal growth factor receptor 2 (HER2). "The high expression of ANP32E is in association with better prognosis, contributing to the proliferation and tumorigenesis of triple-negative breast cancer cells." (PMID 34660776, 2021). "For example, in triple-negative breast cancer, Anp32e is known to enhance the expression of transcription factor E2F1 and induce tumorigenesis." (PMID 36263179, 2022). "In a similar context, ANP32E is found to induce oncogenesis of triple-negative breast cancer (TNBC) by upregulation of the transcription factor, E2F1." (PMID 32605309, 2020). "While ANP32E, AURKB and BCL11A induce tumor progression in triple-negative breast cancer cells, downregulation of CDK2-AP1 enhances tumor growth through cell cycle regulation." (PMID 37007972, 2023).
lung carcinoma (3 papers, 2020 to 2024). "Through our analysis, we also found other eight proteins (ACAT2, PSIP1, TCERG1, DPYSL5, TUBA1A, AKR1B1, ANP32E, and TXNDC17) that have been associated with other cancers, but not in lung cancer." (PMID 32351780, 2020).
myeloma (3 papers, 2018 to 2021). "ANP32E has been shown to play a role in chromatin remodeling and regulate transcription and may contribute to the increased cellular transcriptional dysregulation in myeloma." (PMID 33572851, 2021).
thyroid cancer (2 papers, 2022 to 2024). "In thyroid cancer, the expression of Anp32e is upregulated and promotes the proliferation and migration of thyroid cancer cells by activating the AKT/mTOR/HK2 signaling pathway." (PMID 36263179, 2022).
breast tumors (1 paper, 2021). "ANP32E may function similarly in breast tumors, influencing the binding of key oncogenic transcription factors, such as FOXA1." (PMID 34922480, 2021).
cervical cancer (1 paper, 2025). A primary or metastatic malignant neoplasm involving the cervix. "The differences in ANP32E expression in esophageal cancer, when compared to other cancers, may indicate a potential therapeutic target, offering critical insights for the formulation of treatment strategies in cervical cancer." (PMID 40438679, 2025).
fibrosarcoma (1 paper, 2017). A malignant mesenchymal fibroblastic neoplasm affecting the soft tissue and bone. "ANP32E protein was also found to be downregulated in the cytoplasm of mouse fibrosarcoma cells." (PMID 28220627, 2017).
malignant mesothelioma (1 paper, 2025). A malignant neoplasm of the pleura or peritoneum, arising from mesothelial cells. "One previous in silico analysis showed that the concurrent expression of ANP32E and CIP2A was a poor prognostic factor in patients with malignant mesothelioma." (PMID 39852534, 2025).
osteosarcoma (1 paper, 2024). A usually aggressive malignant bone-forming mesenchymal neoplasm, predominantly affecting adolescents and young adults. "In this study, we investigated whether ANP32e plays a role in regulating cell proliferation in the U2OS human osteosarcoma cell line." (PMID 38482865, 2024).
ovarian carcinoma (1 paper, 2021). A malignant neoplasm originating from the surface ovarian epithelium. "Combining TCGA ovarian cancer dataset, we identified differentially expressed marker genes that were significantly associated with prognosis of ovarian cancer, including ANP32E, STAT1, GPRC5A, EGFL6, PMP22, FBXO21, and CYB5R3." (PMID 34660776, 2021). "The low expression of ANP32E, STAT1, GPRC5A, EGFL6, and PMP22 was positively associated with overall survival time of ovarian cancer." (PMID 34660776, 2021). "The low expression of FBXO21, ANP32E, and CYB5R3 was significantly associated with longer recurrence-free survival time of ovarian cancer." (PMID 34660776, 2021). "We found that the expression levels of STAT1, ANP32E, GPRC5A, and EGFL6 were all significantly higher in ovarian cancer tissues compared with normal tissues." (PMID 34660776, 2021). "Furthermore, marker genes, STAT1, ANP32E, GPRC5A, and EGFL6, were highly expressed in ovarian cancer, while PMP22, FBXO21, and CYB5R3 were lowly expressed in ovarian cancer." (PMID 34660776, 2021).
renal fibrosis (1 paper, 2022). A final common manifestation of a wide variety of chronic kidney diseases characterized by glomerulosclerosis and tubulointerstitial fibrosis. "We also investigated the role of Anp32e protein in the enhanced deposition of renal fibrosis-related proteins (Fn, Col-I) both in vivo and in vitro." (PMID 36263179, 2022). "Linear regression analysis of IHC and Masson's trichrome staining revealed a positive correlation between the areas of Anp32e expression and renal fibrosis." (PMID 36263179, 2022).
ulcerative colitis (1 paper, 2020). An inflammatory bowel disease involving the mucosal surface of the large intestine and rectum. "Despite Anp32e-deficient mice display no sign of disease, it has not to be excluded the role of Anp32e in a model of gut inflammation mimicking ulcerative colitis." (PMID 32709038, 2020).
tumor (14 papers, 2017 to 2026). "Taken together, these results suggest that ANP32E may generally function to restrict chromatin changes at the beginning stages of tumor development, and loss of ANP32E promotes tumor progression by enabling more aggressive cancers." (PMID 34922480, 2021). "Previous studies from our laboratory have identified four genes (ANP32E, DSC2, ANKRD30A and IL6ST/gp130) that are specific to TNBC and were associated with lymph node metastasis (LNmets), the earliest indicator of tumor progression via distal spread." (PMID 35387118, 2022). "We find that one potential driver of this effect, the histone chaperone ANP32E, is inversely correlated with tumor progression and relaxation of chromatin at FOXA1 binding sites." (PMID 34922480, 2021). "In the second pathway, the target gene ANP32E is modified by DNA methylation to downregulate its expression and retard tumor migration." (PMID 32211020, 2020). "Further, we observed that ANP32E is a critical factor in tumor progression in that it induces tumorigenesis by promoting cell cycle progression, which explains why ANP32E expression predicts poor outcomes in TNBC." (PMID 29633513, 2018). "For example, ANP32E (induced by MG132) is a histone chaperone that regulates H2AZ deposition to modulate chromatin accessibility at FOXA1 binding sites and this is inversely associated with tumor growth in ER-positive breast cancers." (PMID 38625038, 2024). "All these implied that ANP32E inhibition suppressed tumor proliferation in TNBC." (PMID 29633513, 2018). "ANP32E overexpression induces G1/S phase transition and promoted tumor proliferation in TNBC cells." (PMID 29633513, 2018). "Furthermore, we discovered that ANP32E promotes tumor proliferation in vitro by inducing G1/S transition, and ANP32E inhibition suppresses tumor formation in vivo." (PMID 29633513, 2018). "Our data suggest that while miR‐141 might function as a tumor suppressor, ANP32E functions as a positive regulator of tumor growth and metastasis." (PMID 28220627, 2017). "In addition, the histone chaperone ANP32E, which has been shown to be inversely correlated with tumor progression and relaxation of chromatin at FOXA1 binding sites, was found to be higher in GATA3mut cancers, which is in keeping with published literature (LogFC = 1.09, FDR = 2.2 × 10–4)." (PMID 40439821, 2025). "Moreover, forced downregulation of ANP32E suppressed TNBC tumor growth in xenograft models." (PMID 34922480, 2021). "PGG dose-dependently inhibited the ANP32E/KDM3B/EGFR axis in vitro and suppressed tumor growth in vivo." (PMID 41980942, 2026). "To further study the molecular mechanisms of ANP32E in tumor progression, we performed a GSEA, which showed that high levels of ANP32E significantly correlated with E2F1‐related gene signatures." (PMID 29633513, 2018). "Meanwhile, no alteration occurred in tumor weight and volume of mice injected with PC cells that had been transfected with miR-202-5p mimic-NC, si-ANP32E-NC, ANP32E-NC, NORAD-NC and co-transfected with miR-202-5p mimic and ANP32E or NORAD and miR-202-5p mimic." (PMID 34551785, 2021).